INS (insulin)
Diseases named in the same sentence as INS in open-access papers (continued):
Sharing a sentence is not in itself a finding about the gene and the disease.
diabetes (continued). "Similarly, hypercholesterolemia’s association with diabetes is characterized by elevated LDL cholesterol levels, which impair insulin sensitivity and beta-cell function, pivotal in diabetes development, explaining its contribution to diabetes risk in the current study." (PMID 38516406, 2024). "Moreover, an RCT showed that daily 360 μg of MK-7 for 12 weeks in insulin-dependent patients with diabetes improved significantly fasting glucose levels, glycated hemoglobin, insulin concentrations and homeostatic model assessment for insulin resistance (HOMA-IR)." (PMID 39881683, 2024). "Notably, MAFLD demonstrates a close association with type 2 diabetes mellitus (T2DM) and obesity, as they share common pathophysiological mechanisms involving insulin resistance, heightened oxidative stress, perturbed hepatic glucose regulation, and impaired lipid metabolism." (PMID 39764250, 2024). "Type 2 diabetes mellitus (T2DM) accounts for 90% of all cases of DM and is characterized by insufficient insulin secretion by pancreatic islet cells, tissue insulin resistance (IR) and an inadequate compensatory insulin secretory response." (PMID 38817391, 2024). "Indeed, susceptibility loci for T2D identified through GWAS with few exceptions have been found to be associated either to a low risk of developing diabetes or mostly prone to affecting β-cell function rather than insulin sensitivity." (PMID 38942960, 2024). "Diabetes mellitus (DM), a set of metabolic disorders, is characterized by persistent high blood glucose levels because of errors in insulin secretion, its action, or both." (PMID 39472961, 2024). "Therefore, the clinical utility of PRS for diabetes should be assessed combining other clinical risk factors, such as BMI (body mass index), GADA (glutamic acid decarboxylase antibodies), and fasting glucose and insulin." (PMID 38294727, 2024). "The inability to produce cortisol, as an insulin counterregulatory hormone, and an insufficient glucocorticoid replacement dose could explain low blood glucose values at the onset of diabetes (87 mg/dL; 4.87 mmol/L; normal reference range 60-100 mg/dL; 3.9-5.6 mmol/L)." (PMID 39091607, 2024). "Diabetes mellitus (DM) is defined as chronic hyperglycemia with insufficient insulin function; its microvascular and macrovascular complications can cause life-threatening events." (PMID 39238763, 2024). "Diabetes mellitus (DM) is an endocrine metabolic disorder characterized by high blood glucose levels, resulting in impaired insulin secretion/action." (PMID 38529398, 2024). "Therefore, the development of oral insulin formulations could provide practical therapeutic tools in the treatment of diabetes." (PMID 39000136, 2024). "Limited data from human-based studies reveal that resveratrol improves blood pressure, waist circumference, insulin sensitivity and fasting glucose levels in patients with type 2 diabetes mellitus and may improve inflammatory status in individuals with obesity." (PMID 38337711, 2024). "Furthermore, repeated insulin usage may help mitigate diabetes-related atrial fibrotic remodeling and the development of AF." (PMID 39541171, 2024). "In some cases, insulin therapy may not be sufficient in managing the diabetes progression and its associated complications." (PMID 39014283, 2024). "Thus, removing barriers to insulin use, including cost, is key to avoiding poor diabetes outcomes." (PMID 36992575, 2024). "The two most common types of diabetes stem from either the pancreas's inability to produce insulin (DM1) or reduced tissue sensitivity to insulin (2 DM), both leading to disrupted carbohydrate metabolism." (PMID 39583130, 2024). "However, in patients undergoing RSG, those without the A allele experienced better anthropometric and insulin level improvements, reducing diabetes risk after 12 months." (PMID 39125390, 2024).
diabetes (continued). "Diabetes mellitus (DM) is characterized by an absolute decline in insulin secretion and peripheral resistance and is the most prevalent metabolic and endocrine disorder." (PMID 38255714, 2024). "Since the COVID‐19 pandemic, CGM and sensor‐augmented insulin pump therapy may be a helpful tool for sending results to health professionals for review and discussion in a consistent manner and inform treatment strategies for managing diabetes." (PMID 37551735, 2023). "Our findings also show that: regardless of the need for insulin treatment, AF patients with diabetes feature a significantly lower survival compared with those without diabetes; diabetic patients on insulin have an 83% higher all-cause mortality vs diabetic patients not on insulin." (PMID 35976428, 2023). "Furthermore, when individuals with diabetes are treated with insulin by s.c. injection, lower levels of insulin reach the liver and higher levels reach peripheral tissues compared with the distribution of endogenous insulin in healthy individuals." (PMID 36404376, 2023). "The detailed understanding of the specific aspects of insulin self-injection that patients find most challenging can help healthcare professionals develop tailored interventions that target the specific needs of each patient, ultimately leading to better management of diabetes." (PMID 37474582, 2023). "Also, leptin and insulin regulate each other in blood‐glucose homeostasis, whereby restricted leptin signaling can induce hyperglycaemia and hyperinsulinemia, ultimately leading to diabetes mellitus." (PMID 37920118, 2023). "The component involving diabetes mellitus (DM) on insulin is an indirect marker of poor perioperative glycemic control." (PMID 37035307, 2023). "Therefore, introducing insulin in patients affected by diabetes can regulate glucose levels." (PMID 37765234, 2023). "Diabetes mellitus (DM) is a serious chronic metabolic disease that is characterized by hyperglycemia resulting from defects in insulin secretion, insulin action, or both." (PMID 37240430, 2023). "Diabetes mellitus (DM) represents a group of chronic metabolic diseases characterized by defective insulin secretion and insulin resistance, which determines increased blood glucose, a condition called hyperglycemia." (PMID 37998956, 2023). "While advancements in the treatment of diabetes continue to rapidly evolve, many of the newer technologies have financial barriers to care, opposing the egalitarian ethos of Banting who sold his patent on insulin for a nominal cost to allow it to be made widely available." (PMID 38033993, 2023). "In this secondary analysis of DPT-1 data, time trajectories of beta cell function and insulin sensitivity were analysed in participants who progressed to type 1 diabetes (progressors) to address the impact of age on patterns of metabolic progression to diabetes." (PMID 36459177, 2023). "Diabetes mellitus (DM), a hyperglycemic condition, occurs due to the failure of insulin secretion and resistance." (PMID 37005639, 2023). "Building on this research, the aim of the current pilot study was to screen patients diagnosed with chronic or aggressive periodontitis for dysglycemia (prediabetes/diabetes) on the hypothesis that CP and AP will show differences in terms of their insulin sensitivity and secretion patterns." (PMID 36651310, 2023). "However, in diabetes, internalizing disorders were only elevated in adolescents who were manipulating their insulin dose, whereas rates of psychiatric comorbidity in adolescents without management problems were comparable to adolescents without a chronic illness." (PMID 36902714, 2023). "Similarly, precious little variation in the outcome of diabetes in the general human population is due to genetic variants in the insulin gene, and yet few would argue that insulin is not an important variable in understanding and treating diabetes." (PMID 37661742, 2023).
diabetes (continued). "The increase in weight in patients with diabetes can have important repercussions on therapeutics (insulin resistance), however the weight in T1D can also be a marker of a good glycemic control through the insulin capacity to increase the lipogenesis in hepatocytes." (PMID 38188912, 2023). "Metformin (MET), an oral biguanide insulin-sensitising drug, is the most widely used treatment for type 2 diabetes mellitus (DM)." (PMID 36598818, 2023). "In addition, diabetes self-management, which typically entails the perpetual management of blood glucose levels and sometimes taking insulin injections, may increase emotional burden and mental disturbances, which can result in depressive and anxiety symptoms." (PMID 37764713, 2023). "The mean duration of diabetes mellitus (DM) was 14.33 ± 8.73 years, and HbA1c was 6.93 ± 1.52% (under 13.33% of insulin treatment and 86.66% of oral hypoglycemic agent medication alone)." (PMID 37497120, 2023). "Diabetes Mellitus (DM) is a disease of chronic nature that occurs as a result of either the human body’s inability to produce enough insulin hormone or the human body is unable to use the insulin produced by the pancreas." (PMID 37976282, 2023). "However, over time, the excessive secretion of insulin causes β-cell exhaustion, and gradually, type 2 patients can no longer deal with diabetes but become more and more dependent on the supplement of exogenous insulin." (PMID 38004234, 2023). "Diabetes mellitus (DM) is a disorder of carbohydrate, protein and fat metabolism brought about by absolute or relative insufficiency of insulin secretion and impaired insulin utilization, characterized mainly by hyperglycemia." (PMID 36749274, 2023). "Diabetes mellitus (DM) is a metabolic disorder that is characterized by chronic hyperglycemia due to defects in insulin secretion, insulin action, or both." (PMID 36843610, 2023). "Likewise, attenuation of mitochondrial ROS production preserves sensitivity to insulin, altogether demonstrating the importance of proper insulin signaling and a balanced redox environment in cellular functioning and the prevention of diabetes-related metabolic abnormalities." (PMID 38137892, 2023). "Insulin treatment may be necessary if diabetes cannot be controlled with oral medication." (PMID 37628857, 2023). "Furthermore, among persons with type I or II diabetes, those with insulin resistance may require higher doses of insulin to control blood glucose levels than those with higher insulin sensitivity." (PMID 38132710, 2023). "This distinction between the glycemic and insulin axis is consistent with the hypothesis that 2-AAA is an early marker or driver of hyperinsulinemia and is associated with elevated insulin before the development of overt hyperglycemia or diabetes." (PMID 37745703, 2023). "T1DM patients should be given an additional dose of insulin three hours after consumption of high carbohydrate and high-fat food because it can lower the concentration of triglycerides and tumor necrosis factor-alpha (TNF alpha), which has been linked to insulin resistance, obesity, and diabetes." (PMID 38111457, 2023). "The pathophysiology of this link is complex; longstanding diabetes is a known risk factor for PDAC, and new evidence suggests that pancreatic cancer may also cause diabetes through a paraneoplastic syndrome or direct effects on islets and insulin secretion." (PMID 37173876, 2023). "When diabetes occurs is usual to find low irisin concentrations, suggesting that glucose may be a critical suppressor of irisin synthesis in skeletal muscle, but the insulin resistance is a previous step in impaired glucose metabolism." (PMID 37448465, 2023). "Adults with diabetes have larger apolipoprotein(a) isoforms versus those without diabetes, a difference that may be caused by the effects of high insulin levels on the synthesis of apolipoprotein(a) in the liver." (PMID 37492110, 2023).
diabetes (continued). "Also, a genome-wide analysis of the DNA methylation quantitative trait locus (mQTL) in human pancreatic islets revealed 383 CpGs (0.08% of tested CpGsites), showing significant associations including known diabetes loci, e.g., ADCY5, KCNJ11, HLA-DQA1, INS, PDX1 and GRB10." (PMID 38136971, 2023). "Diabetes mellitus (DM) is a group metabolic disorder characterized by chronic hyperglycemia resulting from defects in insulin secretion, function, or both." (PMID 36599905, 2023). "A clinical trial included twenty-one normotensive patients with microalbuminuria demonstrated that combined human C-peptide (600 nmol/24 h) and insulin administration for 3 months might improve the kidney function by decreasing the urinary albumin excretion in patients with type 1 diabetes mellitus." (PMID 37033221, 2023). "Although we matched the GV-H and GV-L groups according to age, gender, diabetes duration, BMI, daily insulin dosage, FBG, HbA1c, and CP levels to minimize the confounding factors, the results may be underpowered for the detection of certain biomarkers specific to GV." (PMID 36771224, 2023). "Diabetes mellitus (DM) is a chronic hyperglycemic state characterized by defects in insulin secretion or/and insulin action and has become a major public health challenge worldwide." (PMID 37147636, 2023). "In addition, in vivo transplantation of differentiated β-cells into animal models of STZ-induced diabetes revealed their survival and engraftment as well as glucose-sensitive production of insulin within the host microenvironment, at over 4 weeks after transplantation." (PMID 37644502, 2023). "Diabetes mellitus (DM) is a chronic metabolic disease, characterized by persistent hyperglycemia resulting from diminished insulin secretion or insulin resistance." (PMID 37848702, 2023). "In addition to this, lower health literacy and reduced access to high-quality diabetes care, healthy foods, and diabetes technology (e.g., insulin pumps and continuous glucose monitoring) can all contribute to an increased likelihood of glycaemic dysfunction (and therefore increased DKA risk)." (PMID 37720598, 2023). "Therefore, further studies are needed to clarify whether obesity is the main risk factor for the development of cancer and whether the presence of diabetes itself or the use of exogenous insulin contributes to the development of cancer." (PMID 37065759, 2023). "Indeed, while diabetes status was the main donor characteristic that correlated with changes in insulin secretion, we noted that in T2D sex and age were two donor characteristics showing trends toward an effect on insulin secretion." (PMID 36690328, 2023). "Studies in animal models in which diabetes was induced, showed dysregulation in the expression of pSer473-Akt in the epithelial cells of the proximal tubule, which was also accompanied by a decrease in the expression of megaline and cubicin, which established an insulin and proteinuria ratio." (PMID 37675359, 2023). "Oral glucose lowering drugs (Metformin) may be considered in obese women with type 2 diabetes mellitus to increase insulin sensitivity but need to be prescribed cautiously due to crossing the placenta and lack of long-time follow up data of the offspring (shared decision making)." (PMID 37101033, 2023). "Diabetes mellitus (DM) is defined as a group of metabolic disorders characterized by the decrease in insulin secretion by pancreatic islet cells leading to high blood glucose levels (hyperglycemia)." (PMID 36770385, 2023). "Diabetes mellitus (DM), characterized by hyperglycemia due to decreased insulin production and sensitivity, is a chronic condition." (PMID 37746464, 2023). "Diabetes mellitus (DM) has a complex and multifactorial etiology, involving genetic and environmental components, resulting from altered insulin production by the pancreas and/or inability to adequately exert its function in the body." (PMID 38029230, 2023).
diabetes (continued). "Diabetes is a multifactorial disease caused by a lack of insulin or insulin resistance." (PMID 37637592, 2023). "Insulin-treated individuals who feel highly empowered by their healthcare providers may feel more in control of their diabetes, and as a result, become more involved in disease management, resulting in lower HbA1c levels, thus highlighting the role of continuous support from healthcare providers." (PMID 37264625, 2023). "Metabolic syndrome (e.g., increased blood sugar, decreased insulin sensitivity/insulin resistance), decreased ATP synthesis, reduced mitochondrial function, increased visceral adipose tissue, diabetes, cancer, atherosclerosis, etc., may result also from NAD+ decrease with age." (PMID 36769283, 2023). "The peach [Prunus persica (L.)] tic gum polysaccharide (PGP) could restore the postprandial blood glucose levels in STZ-induced diabetic mice by recovering pancreaislets, and activating the expression of HO-1 and insulin, which are all beneficial for improving diabetes." (PMID 37497112, 2023). "The metabolic environment as well as the changes that accompany obesity and diabetes are complex, and many hormonal alterations likely contribute to impaired lactation, including systemic and localized elevations of adipokines like leptin, inflammatory cytokines, and insulin." (PMID 37173058, 2023). "Persistent hyperglycemia is a hallmark of the metabolic syndrome known as diabetes, which develops when the pancreas either produces insufficient insulin (insulin secretion insufficiency) or when the body no longer effectively uses insulin (insulin resistance)." (PMID 37240812, 2023). "Type 2 diabetes mellitus is based on mechanisms consisting in the development of resistance to insulin in target cells (hepatocytes, adipocytes, skeletal muscle cells), resulting in the termination of an adequate response of these tissues to interaction with insulin." (PMID 36860209, 2023). "We present an in vitro coculture model based on immortalized insulin-producing beta-cell lines with human endothelial cells in 3D spheroids that aims to recapitulate the islet morphology in an effort towards developing a standardized cell model for in vitro diabetes research." (PMID 38162632, 2023). "Moreover, recent network pharmacology focusing on XYS showed that XYS exerted an improved effect on both diabetes and depression involving simultaneous regulation of multiple pathways, such as immune inflammatory reactions, insulin and its receptors (PI3K-AKT), and the cAMP signaling pathway." (PMID 37046230, 2023). "Diabetes mellitus (DM), a disease in which the metabolism of carbohydrates is affected, decreases the body’s ability to generate or accept insulin, as well as its ability to maintain appropriate levels of glucose in the blood." (PMID 38022061, 2023). "In our study, the percentage of pre-sarcopenia in diabetes with insulin sensitizers was lower than those with other anti-diabetic medication (15.85% vs. 18.86%, P = 0.499), yet there was no statistical difference because of the small sample size of insulin-sensitizers subgroup (n = 82)." (PMID 37330547, 2023). "Other than the chemical drugs currently used to treat diabetes, natural plant foods such as fruits and vegetables, which are rich in nutrients such as antioxidants and polyphenols, can improve adipokines and oxidative stress, significantly improving beta cell function and insulin sensitivity." (PMID 36839280, 2023). "Furthermore, abnormally increased insulin secretion in pancreatic β-cells results in hyperinsulinemia, which is the primary driver of metabolic syndrome and related diseases such as obesity and diabetes." (PMID 38132710, 2023). "Further investigations exhibited that the threshold value of the factor for this patient developing diabetes increases by three folds, indicating that the lower insulin resistance and reduced up-regulated beta-cell response may increase the tolerance of an individual to the obesogenic environment." (PMID 36848379, 2023).